INS (insulin)
Diseases named in the same sentence as INS in open-access papers (continued):
Sharing a sentence is not in itself a finding about the gene and the disease.
Hyperglycemia (continued). "The stimulation of SREBP1c due to insulin resistance and hyperglycemia increases the rate of de novo fatty acid synthesis through activation of lipogenic enzymes such as fatty acid synthase (FAS) and acetyl-CoA carboxylase (ACC)." (PMID 34679681, 2021). "T1D is described as a chronic autoimmune disease against insulin-producing β-cells leading to hyperglycemia." (PMID 34079523, 2021). "Anti-diabetic effects of resveratrol (lowering of FBG, elevated GSIS, and improvements in circulating insulin levels) have been noted in rodent models of hyperglycemia, glucose intolerance, and T2DM." (PMID 35098034, 2021). "T2D is a metabolic disorder characterized by chronic hyperglycemia and defects in insulin secretion, insulin action, or both." (PMID 34650392, 2021). "For hyperglycemia compensated by diet (GDM G1) or insulin treatment (GDM G2), slight differences were seen for LF and IgG, but not for SIgA and IgM, during an early stage of lactation only." (PMID 33801292, 2021). "A state of high blood glucose concentration or hyperglycemia, occurring from inadequacies in insulin secretion, action, or both is a complex chronic condition that positions patients at high risk for long-term macro- and microvascular complications." (PMID 34071977, 2021). "Neonatal diabetes mellitus (NDM) is defined as insulin-requiring persistent hyperglycemia occurring within the first 6 months of life, which can result from mutations in at least 25 different genes." (PMID 34566892, 2021). "Dietary fiber has been reported to suppress the postprandial blood glucose elevation and insulin sensitivity by delaying glucose absorption and promoting increased insulin sensitivity at the cellular level, thereby improving hyperglycemia." (PMID 34205359, 2021). "This is further enhanced by the direct effect of insulin and hyperglycaemia on osteoblasts and osteoclasts." (PMID 34884334, 2021). "A Wistar rat study indicated the ability of LWDHW to stimulate insulin secretion and to improve the hyperglycemia condition." (PMID 34457016, 2021). "The results of recent studies showed that administration of 20E act preventively against hyperglycemia in insulin-resistant rats by decreasing hepatic glucose consumption." (PMID 34681728, 2021). "Cannabinoids like CBD and THC have been suggested to reduce hyperglycemia and increase insulin production in rodents, but this has yet to be investigated in a canine model." (PMID 34336977, 2021). "Patients with COVID-19 had higher ICU stays, were on artificial nutrition for longer (p = 0.004), and needed more frequently insulin infusion therapy (p = 0.022) to control stress hyperglycemia." (PMID 34578888, 2021). "GLP-1 receptor binding promotes glucose-dependent pancreatic beta cell insulin release improving hyperglycemia as well as beta cell health to prevent diabetes progression." (PMID 34298687, 2021). "Bloating is the most common digestive system adverse reaction of acarbose, but previous studies have shown that acarbose can easily lead to hyperglycemia and hypoglycemia when used together with sulfonylureas, metformin, or insulin." (PMID 34095252, 2021). "The proinflammatory features of hyperglycemia make it difficult to separate the effects of increasing insulin from its glucose-lowering effects in participants with T2DM." (PMID 33691751, 2021). "GCK-MODY is characterized by a mild hyperglycemia, mainly due to a higher blood glucose threshold for insulin secretion, and an up-regulated glucose counterregulation." (PMID 35069449, 2021). "This condition occurs when the body cells cannot effectively utilize insulin, resulting in hyperglycemia and insulin overproduction." (PMID 34299638, 2021). "A single exposure to a 60-Hz EMF induced hyperglycaemia in both animal groups, and an attenuated second serum insulin peak." (PMID 34083675, 2021).
Hyperglycemia (continued). "Due to their mechanism of action—improvement in hyperglycemia, insulin sensitivity, decreased body weight—there were also expectations for their beneficial effect on cancer risk." (PMID 33562380, 2021). "Control of hyperglycemia through insulin infusion was tested in patients in the UK Glucose Insulin in Stroke Trial (GIST UK) and the SHINE trial." (PMID 34054705, 2021). "Although her respiratory status was stable and did not require treatment for COVID-19, she required high doses of insulin to normalize hyperglycemia and spent two days in the intensive care unit (ICU)." (PMID 33604221, 2021). "This study investigates the effects of hyperglycemia on catecholamines' metabolism in kidney tissue from control, diabetic, and insulin-treated diabetic rats, both in vivo and in vitro." (PMID 34060586, 2021). "An analysis of birthweights in 23 families with GCK-MODY found that where the mother had GCK-MODY and her fetus did not, birthweight was approximately 600 g higher than average due to higher fetal insulin secretion in response to maternal hyperglycaemia." (PMID 33569631, 2021). "A successful islet delivery implant must not only maintain cell survival but also ensure timely release of insulin to prevent postprandial hyperglycemia and overcorrection into hypoglycemia." (PMID 34615868, 2021). "The compounds possessed strong antagonist properties, dose-dependently reducing glucagon-mediated cAMP production and insulin secretion together with counteracting glucagon-mediated hyperglycaemia in vivo." (PMID 34093449, 2021). "Growing evidence has characterized the beneficial effects of acidic fibroblast growth factor (aFGF) and shown that it relieves hyperglycemia, increases insulin sensitivity, and ameliorates neuropathic impairment." (PMID 33479232, 2021). "In fact, the inhibition of DPP-IV prolongs the incretins half-life, resulting in enhanced insulin secretion and reduced hyperglycemia." (PMID 34205680, 2021). "The most common AE other than hyperglycemia was diarrhea (incretin-based therapy, 28.9%; insulin, 30.2%)." (PMID 34275099, 2021). "With an increase in blood glucose levels and the continuous stimulation of hyperglycemia, the function and quality of pancreatic β cells reduced progressively, giving rise to abnormal insulin secretion in T2DM." (PMID 34699323, 2021). "Maternal hyperglycemia was normalized by diet and, in cases when glucose levels remained abnormal, they received metformin and even insulin." (PMID 33803995, 2021). "Acute hyperglycemia is associated with poor outcomes for different acute and chronic diseases including COPD, where progressive insulin-resistance, altered glucose metabolism, and glucose-mediated hormones responses have been deeply characterized." (PMID 33809282, 2021). "Characteristically, T2DM is defined by both insulin resistance and pancreatic beta cell malfunction, leading to hyperglycemia." (PMID 34360895, 2021). "The model of mice deficient in the 26RFa gene (26RFa–/– B6; 26RFa-KO) was characterized by lower basal insulin levels and higher glucose-stimulated hyperglycemia with impairment in insulin synthesis and unaltered insulin sensitivity." (PMID 34497533, 2021). "Insulin management for patients in the neurocritical care unit with aSAH is challenging as hypoglycemia, hyperglycemia, and intensive insulin therapy (targets 81–108 mg/dL) have all been associated with higher mortality and increased complications." (PMID 33420311, 2021). "The pathological hallmarks of T2D in mammals include: i) the resistance of peripheral tissues to insulin signals, leading to ii) hyperglycemia and compensatory hyperinsulinemia, and iii) impaired/abnormal insulin secretion by pancreatic β-cells." (PMID 33893069, 2021). "Our high glucose infusion rate was meant to overrule the controller in order to create hyperglycemia (> 10 mmol/L) and assess for the occurrence of “rebound” hypoglycemia secondary to the insulin doses used to treat the hyperglycemic excursion." (PMID 32006145, 2021).
Hyperglycemia (continued). "IR is characterised by an inappropriate physiologic response in which insensitivity to insulin results in sustained hyperglycaemia and compensatory hyperinsulinemia, even though there is some criticism around this interpretation." (PMID 33477579, 2021). "Substantial evidence indicates that correction of hyperglycemia with insulin administration reduces hospital complications and decreases mortality in general surgery patients." (PMID 33677649, 2021). "T2DM is a chronic inflammatory disorder characterized by hyperglycemia and impaired insulin signaling and production." (PMID 33692997, 2021). "Previously, medicinal plants such as F. carica, L. sativum, and P. granatum have been discovered to have potential chemical constituents for hyperglycemia and antihyperlipidemia via increased insulin sensitivity and antioxidant mechanisms." (PMID 34970629, 2021). "We have shown that rapid correction of hyperglycemia can greatly improve β-cell function, especially with respect to first-phase insulin secretion." (PMID 34912428, 2021). "Administration of REE (500 mg kg-1) reduced streptozotocin-induced hyperglycemia by 44%, restored serum insulin levels, reestablished Glut2 and Glut4 expression and ameliorated pancreatic tissue damage in diabetic rats." (PMID 34358274, 2021). "He presented with hyperglycemia on the first day of life, which was managed with parenteral insulin infusion." (PMID 34422424, 2021). "Hyperglycaemia has also been listed as a probable risk factor for ICUAW development, with intense insulin therapy in the ICU as a possible prevention strategy." (PMID 34621547, 2021). "Glucose supplementation in endotoxemic or polymicrobial sepsis mice impaired both glucose disposal and insulin sensitivity, and induced pancreatic insufficiency leading to hyperglycemia and death." (PMID 34361061, 2021). "and the known metabolic effects on β-cell function and insulin sensitivity of the different classes of medication may provide a more personalised treatment for patients with T2D based on the main underlying causes of hyperglycaemia in each individual as previously outlined." (PMID 33387681, 2021). "The data show that MLT in dogs can also promote the recovery of hyperglycemia and insulin secretion by ADMSCs in dogs." (PMID 34722505, 2021). "Although insulin resistance is the earliest detectable abnormality in T2D, dysfunction in the insulin secretory capacity is the major determinant of hyperglycaemia and onset of T2D." (PMID 33794975, 2021). "Insulin and C-peptide were generally elevated in HI vs LO but the fold rise during hyperglycaemia was similar." (PMID 33241460, 2021). "T2DM is a chronic disease characterized by hyperglycemia and progressive dysregulation of the insulin-glucose feedback mechanism, and glucose-lowering is a mainstay of treatment." (PMID 34681215, 2021). "The authors also reported that Fst gene delivery to older mice with hyperglycemia and declining insulinemia led to significant restoration of serum insulin concentration." (PMID 33897620, 2021). "The results indicated that GPR43 KO increased Akt protein phosphorylation in podocytes in diabetic mice, suggesting that GPR43 depletion ameliorated the insulin signalling in podocytes with the hyperglycaemia background." (PMID 33754024, 2021). "In hyperglycemia, insulin secretion is increased, and glucagon secretion is suppressed, whereas, in hypoglycemia, insulin secretion is inhibited, and glucagon secretion is increased, causing an increase in hepatic glucose production." (PMID 34199839, 2021). "Education included the impact of hyperglycaemia, diet and lifestyle, and training on self-monitoring of blood glucose and insulin injection administration." (PMID 34111207, 2021). "Our simulations have shown that the control-to-range algorithm used in the clinical practice (SMBG-Rule) is effective in titrating the long-acting insulin dose by reducing both hypoglycemia and hyperglycemia." (PMID 35082757, 2021).
Hyperglycemia (continued). "In principle, multiple inhibitions of PTP1B and glycoside hydrolase proteins are a promising strategy to simultaneously suppress hyperglycemia and improve insulin sensitization." (PMID 34204232, 2021). "Pregnant women with well-controlled blood glucose tend to generate fetuses of appropriate weight for gestational age, as maternal hyperglycemia increases insulin secretion in the fetal pancreas." (PMID 33513843, 2021). "The insulin-loaded nCOF exhibited insulin protection in digestive fluids in vitro as well as glucose-responsive release, and this hyperglycemia-induced release was confirmed in vivo in diabetic rats without noticeable toxic effects." (PMID 33995999, 2021). "One study that reported on the impact of a change in clinical practice, aimed at limiting dextrose intake (to minimum of 4 mg/kg/min), demonstrated a reduction in the prevalence of hyperglycaemia, use of insulin and mortality." (PMID 34368024, 2021). "Evidence suggests that higher insulin sensitivityreduces hyperglycemia, hepatic lipid synthesis and fataccumulation in adipose tissues." (PMID 33497048, 2021). "Each insulin-sensitive tissue presents abnormal characteristics that contribute to hyperglycemia in an insulin-resistant state." (PMID 35002743, 2021). "Overnutrition induces an initial increase in insulin secretory activity of β-cells in attempt to balance the systemic hyperglycaemia." (PMID 33578952, 2021). "S100B KO mice show less hyperglycemia, higher glucose tolerance and insulin sensitivity, and reduced β cell death, but with similar levels of insulin compared to controls." (PMID 33671490, 2021). "After a brief surgical recovery period (approximately 2 weeks), the mice were injected with (+)-D-glucose to induce hyperglycemia and serum was collected after 30 min to measure human insulin in serum using an ELISA." (PMID 34055806, 2021). "On the other hand, the increase in plasma insulin levels after a meal was shown to be a prerequisite (along with hyperglycemia and low plasma NEFA levels) for the postprandial suppression of ghrelin." (PMID 33419065, 2021). "On top of that, it has been implicated that the downregulation of sirtuin-1 (SIRT-1) activity induced by persistent hyperglycemia condition and high insulin environment also plays a significant role in the development of diabetic cardiac inflammation." (PMID 34065781, 2021). "Ectopic PDX1 expression in adult human liver cells induced the development of functional insulin-producing cells; these cells when transplanted under the renal capsule of diabetic, immunodeficient mice ameliorated hyperglycemia." (PMID 34882233, 2021). "Glucose tolerance tests showed hyperinsulinemia and hyperglycemia, indicative of insulin insensitivity in the miR-181c/d-/- mice." (PMID 34879063, 2021). "Stimulation of fetal insulin secretion by maternal hyperglycemia lowered fetal glycemia, which, in turn, increased the maternal–fetal glucose gradient, resulting in rapid fetal growth and excess fat deposition." (PMID 34489862, 2021). "This is comparable to the glucotoxicity thought to occur in T2D, where prolonged hyperglycaemia and subsequent demand for insulin leads to a decline in β cell function and an eventual increase in β cell apoptosis, possibly due to oxidative stress." (PMID 34948127, 2021). "Anesthesia was provided by many different anesthesiologists; therefore, a therapeutic approach to hyperglycemia such as the dose of insulin given and at which glucose level the treatment initiation has taken place can vary, possibly influencing the results." (PMID 34830501, 2021). "The consequence is a better control of hyperglycemia and fewer episodes of hypoglycemia related to insulin administration." (PMID 34068151, 2021). "The insulin tolerance test and glucose tolerance test were performed to investigate the influence of curcumin on hyperglycemia-lowering effect in vivo." (PMID 34818970, 2021).
Hyperglycemia (continued). "The phenomenon of fluoride hyperglycemia is also known, resulting from, inter alia, inhibition of insulin secretion by pancreatic β cells and disturbed secretion of thyroid hormones." (PMID 34070884, 2021). "Treating stress hyperglycemia with insulin would commonly require a more compelling glycemic abnormality than the glucose level recommended for screening and documentation." (PMID 34075071, 2021). "Hepatic TG accumulation occurs in parallel with abnormal hepatic energy metabolism, impaired insulin-mediated hepatic glucose suppression, and the production of very low-density lipoprotein, leading to hyperglycemia and hypertriglyceridemia." (PMID 34818372, 2021). "A further decline in insulin sensitivity makes the ß-cells exhausted, leading to hyperglycemia and T2D." (PMID 34421908, 2021). "High glucose (HG)-treated cells significantly increased glucose production after challenge with the lactate/pyruvate mixture for up to 240 min when compared with control, suggesting that hyperglycemia and insulin resistance impair hepatic gluconeogenesis." (PMID 33669133, 2021). "Diabetic ketoacidosis (DKA) is characterized by markedly hyperglycemia and acidosis secondary to the elevation of blood ketones resulting from a shortage of insulin." (PMID 34021486, 2021). "Low circulating NEFA concentration during hyperglycaemia and increased insulin concentration also facilitate a high rate of glucose disposal by exercising muscle." (PMID 34235576, 2021). "TE#1 sessions occurred between 3:30 and 5:00 p.m. in the course of afternoon snack, which allowed us to evaluate the needs for insulin dose corrections in case of hyperglycemia, or fast-acting sugars intake following hypoglycemia." (PMID 34512541, 2021). "Patients with type 1 diabetes (T1D) suffer greatly from uncontrolled hyperglycemia, and insulin delivery remains the only treatment option, but is accompanied with obesity development and life-threatening hypoglycemia." (PMID 33976218, 2021). "Takikawa M., Inoue S., Horio F., Tsuda T. Dietary anthocyanin-rich bilberry extract ameliorates hyperglycemia and insulin sensitivity viaactivation of AMP-activated protein kinase in diabetic mice." (PMID 34901716, 2021). "Hyperglycaemia in patients with DN is due to insufficient insulin secretion in the patient's body or the body's resistance to insulin, and insulin-resistant tissue produces excessive inflammatory cytokines due to hypoxia." (PMID 35971382, 2021). "The active transport of glucose across the BBB was similar between lean and obese individuals, suggesting that peripheral insulin resistance can lead to hyperglycemia in the brain." (PMID 34199898, 2021). "Insufficient insulin secretion will lead to a series of metabolic disorders in vivo such as hyperglycemia, and further aggravate the progression of pancreatic cancer." (PMID 34090418, 2021). "It is accepted that sustained elevation of insulin secretion, such as in hyperglycemia, induces cardiac hypertrophy." (PMID 34835942, 2021). "In such adolescents, insufficient/excessive sleep was associated with hyperglycemia, and a decreased SWS was linked to a decrease in insulin level." (PMID 33658975, 2021). "This IWCS is demonstrated to accurately monitor glucose fluctuations and responsively deliver insulin to regulate hyperglycemia." (PMID 34081407, 2021). "The continuous hyperglycemia forces pancreatic β-cells to increase insulin production until excessive rates for ER capacity." (PMID 34069890, 2021). "Under stress and injuries, this hyperglycemia directly results from raised blood catecholamine levels or increasing glucagon secretion and inhibiting insulin secretion indirectly." (PMID 35095738, 2021). "HFD feeding, which promotes hyperglycemia, continuously activates cPLA2 and produces prostaglandins, and thus induces inflammation in the hypothalamus and attenuates insulin sensitivity in the liver." (PMID 33879780, 2021).